TNF (tumor necrosis factor)
Diseases named in the same sentence as TNF in open-access papers (continued):
Sharing a sentence is not in itself a finding about the gene and the disease.
infection (continued). "The recruitment of neutrophils to the infection site is primarily mediated by cytokines such as IL-8 and TNF-α." (PMID 41294882, 2025). "Due to their capacity for triggering neuroinflammatory responses, lipopolysaccharide (LPS) and tumor necrosis factor-alpha (TNF-α) are commonly used stimuli to mimic aspects of infection in vitro." (PMID 41584742, 2025). "Elevated expression of MALT1 and TNF, two critical mediators of NF-κB signaling, reflects enhanced cellular responses to infection, potentially amplifying immune and inflammatory processes in RAW264.7 cells." (PMID 40248690, 2025). "Previous investigations have also documented that IFN-γ was detectable in only 30% of the cells within the N. brasiliensis mycetoma microabscess by 90 dpi, while TNF-α was undetected throughout the infection period." (PMID 40809173, 2025). "Although CRP levels rise at a slower rate compared to IL-1, TNF-α, and IL-6, they start to increase within 4–6 h after the onset of inflammation or infection and typically reach peak levels within 24–48 h." (PMID 40584620, 2025). "During early infection, dMφ secretes pro-angiogenic factors and cytokines that can either promote inflammation (e.g., tumor necrosis factor [TNF]-α and interleukin [IL]-1β) or suppress it (e.g., transforming growth factor [TGF]-β and IL-10)." (PMID 40597375, 2025). "Following infection with the Eimeria parasite, a significant increase in the mRNA expression levels of the TNF-α gene was observed." (PMID 41479898, 2025). "The fimbriae of Porphyromonas gingivalis facilitate the infection of dendritic cells by the pathogen, inducing the cells to undergo a maturation process with the subsequent production of IL-1β, IL-6, TNF-α, IL-10, IL-12, and IFN-γ." (PMID 39942791, 2025). "The IL-1β, IL-18, and TNF-α protein levels were increased in the infection group compared with the control group (p < 0.001)." (PMID 40305201, 2025). "As stated, during infection, macrophages lead to the massive release of pro-inflammatory cytokines, such as TNF and IL-1β." (PMID 40333197, 2025). "Of the many inflammatory mediators secreted, TNF-α plays a crucial role in the development of severe infection." (PMID 40529149, 2025). "IL-1β is an important component of a series of inflammatory cascades along with TNF-α in response to infection produced by various cells." (PMID 39941110, 2025). "Inflammation is a critical host response to infection, mediated by immune cells such as monocytes and macrophages, which release proinflammatory cytokines (e.g., tumor necrosis factor α (TNF-α), interleukins (IL-1β, IL-6, and IL-8)) upon pathogen recognition." (PMID 40564288, 2025). "Immediately after infection, cells were treated with TNFα, and cell lysates were harvested over a 24 h time period." (PMID 40006946, 2025). "Infection of 3T3-L1-derived adipocytes with Mtb has been shown to induce the secretion of cytokines such as IL-6 and TNF-α at low bacterial concentrations." (PMID 41373747, 2025). "It is suggested that the involved pathological processes result in increased levels of proinflammatory cytokines, such as TNF-α, IL-1 and IL-6, among others, in response to infection." (PMID 40647668, 2025). "A suppressed number of antiviral cytokines like IL-1a, IFN-β, and especially TNF-α is observed in transduced cells after 24 h of infection." (PMID 41157608, 2025). "It is important to note that inflammation and tissue injury occur early after infection, and TNF-α is detectable at day 3 post-infection." (PMID 41321641, 2025). "Several studies indicate an upregulation of myeloid differentiation primary response (MYD) 88-related signaling pathways upon infection of AlvMφ in vitro, leading to increased expression of cytokines (e.g., TNF-α, IL-1β, IL-8, IL-10) and chemokines." (PMID 39796262, 2025).
infection (continued). "HMGB1, an early proinflammatory protein, can be actively secreted under stimulation by Lipopolysaccharide (LPS), TNF-α, infection and endogenous host stimuli or passively released under conditions of cell apoptosis and necrocytosis." (PMID 39883639, 2025). "Golimumab is contraindicated in individuals with hypersensitivity to the drug, prior use of TNF-α inhibitors, active or recurrent infections, a history of malignancies, or concurrent treatment with other immunosuppressive agents." (PMID 40142915, 2025). "Previously, we demonstrated that infection with the BEV HY12 strain causes a cytokine storm with increased levels of pro-inflammatory and inflammatory cytokines, including TNF-α, which is one of the stimulators of the NF-κB activation pathway." (PMID 39956903, 2025). "The immune response to an hMPV infection is characterized by the activation of Th17-like cells, which secrete tumor necrosis factor-alpha TNF-α) and interleukin (IL)-6 in the lungs." (PMID 40176892, 2025). "In our study, both IFN-γ and TNF-α were strongly secreted during infections with Mtb in the late reactivation and log phases." (PMID 41450943, 2025). "In mouse sera post-PCV2 infection also showed elevated levels of IL-6, IL-8 IL-10, TNF-α, and MCP-1 (p < 0.05 or p < 0.01)." (PMID 39968105, 2025). "Several studies have shown that TLR2 and TLR4 recognize components of the fungal wall and contribute to the production of proinflammatory cytokines, such as TNF-α, IL-6, and IL-1β, which promote the recruitment of immune cells to the infection site." (PMID 41590416, 2025). "IFN-γ: activates macrophages; induces IL-6, TNF-α, IL-10 production via JAK-STAT; IFNγR1 deficiency increases infection susceptibility." (PMID 41268545, 2025). "Results showed significant upregulation of TNF-α, IL-1β, IL-6, and IL-8 mRNA levels in Vero E6 cells post-infection." (PMID 40703674, 2025). "Furthermore, among HSPC subtypes in the IS group, we detected a commonly increased expression of hallmark genes related to TNF-α signaling via NFκB, suggesting that IS HSPCs were imprinted with the maternal acute infection event and may have a long-lasting effect on offspring health." (PMID 41436442, 2025). "The current study found that serotype 5 UV strain possessed a higher capacity to resist host immune clearance, replicate, disseminate, and establish infection, subsequently triggering the production of excessive TNF-α in the early stages of infection." (PMID 40574283, 2025). "Infection stimulated the production of inflammatory cytokines, notably leading to a fivefold increase in TNF-α with H37Rv (p < 0.01)." (PMID 41373747, 2025). "In line with the effects on COX-2 protein induction, the p38 inhibitor almost completely blocked the production of PGE2 by GFs stimulated with TNF during infection with P. gingivalis or F. nucleatum." (PMID 40178270, 2025). "In this study, TNF, IL-10 and IL-8 showed an infection-dependent induction, with strong secretion at early time points but, surprisingly, without significant sex-specific differences." (PMID 40794782, 2025). "In the kidneys of immunocompetent Acanthamoeba sp.-infected mice, IFNγ and TNFα were increased only at the beginning of infection, while in the immunosuppressed mice, those cytokines were increased throughout the entire period of infection." (PMID 40586570, 2025). "On the host side, acute infection triggers proinflammatory cascades involving cytokines like TNFα and IL-1β, along with neutrophil extracellular traps (NETs) to contain the infection." (PMID 40725573, 2025). "On the other hand, infection with SFV/TNFα specifically upregulated the amount of IL-6, CCL2, CCL3, CCL7 and CCL20 (p < 0.0001)." (PMID 40547518, 2025). "It was observed that expression of TNF-α and IL-1β significantly enhanced at early time points (24 and 48 h) post-infection." (PMID 40982322, 2025).
infection (continued). "Lc. lactis and Lb. paracasei infections show moderate TNF-α levels (341 pg/mL and 258 pg/mL, respectively) after N treatment by 24h, significantly lower than the control condition (1085 pg/mL and 109 pg/mL)." (PMID 40873569, 2025). "One day after infection, the expression of Cxcl1, Cxcl2, Cxcl5, TNF-α, and IL-1β were 15 – 50-fold higher in lungs of Mki67WT mice exposed to hyperoxia when compared to Mki67WT mice exposed to room air." (PMID 40494897, 2025). "This extract significantly reduced inflammation and prevented infection by inhibiting the release of pro-inflammatory cytokines such as TNF-α and IL-6, thereby protecting mice from lung injuries associated with endotoxin-induced septic shock." (PMID 40144662, 2025). "The chemotactic agents CXCL9 and CXCL10 attract cells to the infection site, which secrete more pro-inflammatory cytokines, such as TNF-α, IL-1β and IFN-γ, amplifying the process and exacerbating the Th1 response." (PMID 40608568, 2025). "Both IL-6 and TNF-α are key signaling molecules released during macrophage activation; elevated concentrations indicate an inflammatory response triggered by infection detection." (PMID 41403880, 2025). "In this work, we demonstrated that HAdV infection induces relocalization of IKKα to the nucleus and showed data that indicate that E1B-55K suppresses TNFα-induced immune responses mediated by the NF-κB pathway during late infection stages." (PMID 40103806, 2025). "TNF-α is an important pro-inflammatory cytokine that plays a key role in immune responses during infection." (PMID 40356900, 2025). "Numerical correlations observed for pre-infection cytokines measured in plasma (IL-1β, TNF-α, IL-6, IL-10, IFN-γ and TGF-β) and viral loads in brain, lungs and heart for animals from all the groups of the experiment." (PMID 40969767, 2025). "Consistent with clinical observations, in vitro infection of RD cells and in vivo infection of suckling mice in our study similarly demonstrated significant upregulation of IL-6, TNF-α, CXCL2, CXCL3, CXCL8 (IL-8), and CXCL10." (PMID 40872743, 2025). "IFN-β was present at very low levels in mice before infection (pre), while TNF-α, IL-1β, and IL-6 were undetectable." (PMID 40124358, 2025). "The number of IFN‐γ‐producing CD8+ T cells and TNF‐α‐producing CD4+ T cells was significantly higher in the 1–5 years group after infection, compared to the 6–10 years group after recovery (p = < 0.0001)." (PMID 39822038, 2025). "The importance of niche cells for maintaining serum Ab durability has been supported by studies using tumor necrosis factor (TNF) treatment and various infection models." (PMID 41357177, 2025). "It is produced in response to infection or tissue injury but can also be induced by death ligands, such as tumor necrosis factor alpha (TNFα), Fas/CD95 ligand, and TRAIL." (PMID 40683891, 2025). "Consistently, the LASSO regression retained five of these six parameters as the strongest predictors of infection status: urea (coefficient = 0.41), IL-10 (0.53), TNF (0.49), CCL3 (0.38), and IL-1β (0.33)." (PMID 41279035, 2025). "Proinflammatory cytokines produced by immune cells in response to infection or injury, such as tumor necrosis factor (TNF) and interleukins (IL), play a significant role in the pathogenesis of respiratory diseases." (PMID 40136649, 2025). "In parallel, PM10 pre-exposure was associated with lower levels of TNF-α, IFN-γ, and IP-10 during Delta variant infection." (PMID 41561095, 2025). "Pa-STING vaccination also significantly reduced levels of IL-1β, IL-6, and TNF-α in the bronchoalveolar lavage (BAL) fluid 20 hours after infection." (PMID 40705476, 2025). "PCN033 infection elevated IL-1β and TNF-α levels in serum, lungs, spleens and brains while reducing TGF-β in serum, lungs, and spleens." (PMID 41295668, 2025). "Following infection, TNFα expression decreased in the gills and heart, but increased in certain tissues, such as the brain and intestine." (PMID 40723580, 2025).
infection (continued). "To further investigate the inflammatory response, we examined plasma levels of IL-1β, IL-6, and TNFα in mice following infection with either wild-type or ΔmsbB ST." (PMID 41304196, 2025). "Correlation analysis highlighted distinct immunological patterns, with IL-10 acting as a negative regulator of inflammation, while TNF-α and IL-17A reflected infection intensity depending on species and timing." (PMID 41156648, 2025). "From the perspective of the color scale, the expressions of IL-8, IL-1β, IL-4, IL-6, IL-2, TNF-α, IL-10, and IL-17 showed a significant upward trend as the infection duration increased." (PMID 41165313, 2025). "The ELISA results revealed that EPEC66 infection significantly increased the levels of the pro-inflammatory cytokines TNF-α, IL-1β, and IL-6 in the ileum, compared with those in the NC group (p < 0.01)." (PMID 41373958, 2025). "GSVA revealed that H37Rv infection intensified TNF signaling activity, whereas BCG enhanced signaling within the Notch and Hippo pathways." (PMID 40738187, 2025). "We observed heightened levels of CD8+ T cell activation and cytokine production, including IFN‐γ and TNF, following infection in young animals compared to mock infected controls." (PMID 39550693, 2025). "These macrophages release various cytokines such as TNF-α and IL-12 that recruit additional immune cells such as neutrophils, T cells, B cells, and dendritic cells to the site of infection." (PMID 40723907, 2025). "The ΔretS infection increased cell death, inflammatory factors (IL-1β, IL-6, TNF-α), and reactive oxygen species compared to a T6SS-inactive strain." (PMID 40557319, 2025). "Protein abundance of TNF-α, IL-1β, and IL-6 increased at 24 h after infection, consistent with mRNA abundance." (PMID 40663568, 2025). "In contrast to T24/83 cells, TK-2 cells failed completely to secrete TNFα upon infection with CFT073." (PMID 41310197, 2025). "It suppresses the production and release of TNF-α and IL-6 in macrophages induced by H. pylori, thereby controlling infection-related inflammatory responses and preventing pathological changes." (PMID 40831563, 2025). "Simultaneously, adverse effects of anti-TNFα therapy, such as infection and malignant tumors, cannot be ignored." (PMID 39856555, 2025). "Pre-infection (day 0), tumor necrosis factor (Tnf) expression was highest in standard diet bats and lowest in suboptimal-fat diet bats, suggesting that diet influenced inflammatory state, regardless of infection." (PMID 39968620, 2025). "During infection, there was a notable increase in the production and release of pro-inflammatory cytokines, including IL-8, TNF-α, and IL-6." (PMID 40101060, 2025). "IL-1β and TNF-α are two important proinflammatory cytokines that participate in the regulation of inflammatory response at the early infection period." (PMID 40963585, 2025). "Like its counterpart in mammals, TNFα in teleosts promotes chemotaxis of neutrophils and monocytes/macrophages to the site of infection, phagocytosis of macrophages and triggers the production of reactive oxygen and nitrogen intermediates." (PMID 40517265, 2025). "TNF-α is involved in a wide range of inflammatory, infectious, autoimmune, and malignant conditions and released in response to infection." (PMID 40722600, 2025). "infection in a cohort of patients living with IMID under treatment with TNF-α inhibitors or other biologics." (PMID 40993715, 2025). "In brief, the model consists of intradermal infection with 104 CFU in the ear, followed by TNF-α neutralization at two and three-weeks post-infection." (PMID 41279700, 2025). "However, a study showed that elevated TNF-α levels are associated with the replication stage of the parasite within the chorionic villus (72 h after infection), which would hinder its transformation into a trypomastigote and consequently limit infection of the fetus." (PMID 40872246, 2025).
infection (continued). "The greatest significant reduction in TNF-α levels occurred in M. avium-infected macrophages treated with 100 μg/mL of FGP or FDSP 8 days post-infection." (PMID 41155292, 2025). "At 3 h post-infection, there were significant reductions in levels of TNF-α following treatment with 100 μg/mL FGP and 1 and 10 μg/mL FDSP." (PMID 41155292, 2025). "We observed that macrophages infected with L. major and treated with GXMGal were able to control the infection; however, TNF-α neutralization led to an increase in the number of parasites." (PMID 41156732, 2025). "In the present research, at 28 days post-infection, CD11d expression was markedly elevated in cardiac tissue, whereas levels of TNF-α, IL-1β, and IL-18 remained within the normal range." (PMID 41472298, 2025). "Similar effects have been observed in in vivo studies, confirming that TNF signaling plays a crucial role in shifting towards glycolytic metabolism in the liver, spleen and monocytic cells of mice upon infection." (PMID 41132685, 2025). "To further investigate the antiviral mechanism of AVI-4206, we measured the abundance of the antiviral cytokines IP-10, IL-2, IL-6, and TNF-α in lung tissue at 4 and 7 days post-infection." (PMID 39149230, 2025). "Knocking-down of FTO retarded the infection induced-decrease in the levels of m6A modification in TNF-α transcripts, accompanied by dampened immune response and uncontrolled T. gondii proliferation." (PMID 40663568, 2025). "When we knocked out C3, we found that inflammatory cytokines such as TNF-α, IL-1β, IL-17A, and IL-6 were upregulated on day 1 post-infection." (PMID 40008883, 2025). "Influenza virus infection can induce DCs to produce inflammatory factors such as TNF-α and IL-6, which play a role in regulating the inflammatory response and attracting other immune cells to the infection site." (PMID 40872644, 2025). "FGP treatment demonstrated a dose-dependent decrease in TNF-α levels 8 days post-infection; FDSP treatment also showed a similar trend." (PMID 41155292, 2025). "The production of IL-1β and TNF-α was also influenced by the presence of copper during infection with the MtbΔctpA mutant strain." (PMID 40002852, 2025). "Targeting tumor necrosis factor (TNF) α with antisense oligonucleotides has demonstrated significant efficacy in combating this infection." (PMID 40563458, 2025). "After infection, TNF-α was increased from day 3 to day 9 (P = 0.003) in control dogs compared to vaccinated animals." (PMID 41159782, 2025). "The main manifestations are dysregulation of T lymphocyte levels and elevated levels of infection-related biomarkers and inflammatory cytokines, including interleukin-1 (IL-1), interleukin-6 (IL-6), and tumor necrosis factor α (TNF-α)." (PMID 41156098, 2025). "Infection with T. spiralis led to a significant increase in arginase-1 and TNF-α gene expression, whereas the relative expression of IL-10 significantly decreased." (PMID 41239511, 2025). "Mice vaccinated against Py17XL show reduced early TGF-β responses and higher IFN-γ and TNF-α levels, leading to quick resolution of subsequent infections." (PMID 39907835, 2025). "Proinflammatory cytokines, such as TNFα, IL-1β, and IL-6, produced after pathogen infection or tissue damage, contribute to mounting an effective immune response." (PMID 40462232, 2025). "In humans, the transcription factor p65 is a central transcriptional activator of pro-inflammatory cytokines, including TNF-α, IL-1β, and IL-6, playing pivotal roles in the response to infection, immune cell activation, and inflammatory resolution." (PMID 41141596, 2025). "After NTHi infection, the TNFα expression was similar in TL2-C29-treated as in MDM controls, indicating that TLR2 does not mediate the expression of TNFα in NTHi-infected MDMs." (PMID 40013145, 2025).